AHR (aryl hydrocarbon receptor)
Diseases named in the same sentence as AHR in open-access papers (continued):
Sharing a sentence is not in itself a finding about the gene and the disease.
tumor (continued). "Its function as a tumor modulator is complex, as AhR can act as pro-tumorigenic or anti-tumorigenic factor depending on the cancer cell type, sometimes, with conflicting reports." (PMID 38807762, 2024). "Increasing evidence highlights AhR’s role as a critical regulator of numerous biological functions, such as cellular differentiation, immune response, metabolism, and even tumor formation." (PMID 39211042, 2024). "AHRR is a recognized tumor suppressor that regulates the activity of AHR, whereas NCOA2 acts as a transcriptional co-activator of nuclear hormone receptors." (PMID 39432588, 2024). "AHR upregulates AR target genes that are involved in tumor proliferation, further complicating treatment strategies." (PMID 39600743, 2024). "Another study established that PXR has a complimentary role alongside aryl hydrocarbon receptor (AHR) inducing DNA damage after exposure of skin to the tumor initiator 7,12-dimethylbenz(a)anthracene (DMBA)." (PMID 39508053, 2024). "Nevertheless, investigations on the distribution of AhR expression, specifically in cancer or immune cells in the tumor microenvironment (TME), remain limited." (PMID 38680496, 2024). "The aryl hydrocarbon receptor (AhR) pathway mediates toxicity and the tumor-promoting properties of environmental contaminants." (PMID 38255999, 2024). "Although there has been very limit research on AhR’s role in tumor lipid metabolism, it is found that AhR influences many of the genes that are up-regulated in tumors and are linked to lipid metabolism regulation, including CD36, SCD-1, SREBP, and FASN." (PMID 38434684, 2024). "Fortunately, the release of NLG919 was responsible for inhibiting the Kyn-AHR channel, and restated the reversal of the tumor immunosuppression microenvironment, thus realizing intelligent nanovesicle-mediated chemoimmunotherapy cycle amplification in PDAC." (PMID 38755645, 2024). "The anti‐tumour effects of some microbial Trp metabolites persisted despite the use of an AhR inhibitor, indicating they act through an AhR‐independent mechanism." (PMID 39568157, 2024). "AhR affects the critical stages of tumorigenesis, such as initiation, progression, and metastasis, and anti-tumorigenesis, acting as a tumor suppressor." (PMID 38791215, 2024). "The repressor of the aryl-hydrocarbon receptor (AHRR) showed an expression profile in line with the current understanding of it as a tumour suppressor being higher expressed in primary tumours versus relapse." (PMID 38361045, 2024). "Studies on aggressive tumors and tumor cell lines have shown that the AhR can be constitutively overexpressed." (PMID 39339278, 2024). "There are a growing number of FDA-approved drugs approved for other indications that have been recognized as AhR modulators, with demonstrated anti-tumor efficacy in pre-clinical studies." (PMID 38807762, 2024). "This bacterium, L. reuteri, colonizes tumor tissue and produces indole-3-aldehyde (I3A), which activates a specific signaling pathway, aryl hydrocarbon receptor (AhR), in CD8+ T cells." (PMID 38547865, 2024). "Contribution of signatures in each cohort is provided on the right; (j–k) Protein abundance of CYP1A1 (j) and AhR (k) in tumor and normal samples within the XWLC cohort; Two-tailed Wilcoxon rank sum test used to calculate p-values in (j–k)." (PMID 39432560, 2024). "Exploring combination therapies that target AhR alongside other pathways critical for tumor growth and survival is another important direction for future research." (PMID 39184676, 2024). "AHR promotes immune evasion and tumor progression, influencing MAP2K1 and PRKACB, which regulate key pathways like MAPK and NF-κB signaling, respectively." (PMID 39835132, 2024). "The aryl hydrocarbon receptor (AhR) is a ubiquitous nuclear receptor with a broad range of functions, both in tumor cells and immune cells within the tumor microenvironment (TME)." (PMID 38339226, 2024).
tumor (continued). "Kyn has been shown to activate the AhR, initiating autocrine and paracrine functions that impact the anti-tumor immune response and tumor cell survival and migration." (PMID 38361941, 2024). "AHR acts as a tumor suppressor in models of colon cancer but promotes the growth and invasiveness of gastric cancer cells." (PMID 39450255, 2024). "One of the areas of interest is targeting AHR in cancer, albeit the role of AHR in cancers is ambiguous as there is evidence for a tumour-suppressive role as well as potential involvement in tumour progression." (PMID 39242971, 2024). "With significant effects on immune function and its direct signaling in tumor cells, activation of AhR has emerged as an important modulator of the tumor immune microenvironment, with both pro- and anti-tumor effects." (PMID 38339226, 2024). "In summary, AhR overexpression helps tumor cells evade the immune system by sending inhibitory signals to the immune cells through the TME." (PMID 38434684, 2024). "On the other hand, there are several approaches underway to inhibit AHR activity in tumour settings, with antagonists targeting the putative suppressive effect of AHR on anti-tumour immunity and resistance to immune checkpoint inhibitors." (PMID 39242971, 2024). "Through the use of nano-delivery technologies, the T cell activator anti-CD28-coupled aryl hydrocarbon receptor (AhR) inhibitor (CH223191) can be encapsulated to modify the tumor immune milieu and successfully prevent tumor cell metastasis." (PMID 38434684, 2024). "Altogether, our work reveals a novel function for AhR in the suppression of tumor-intrinsic, STING-mediated IFN-I production and helps to shed light on the lack of efficacy of PARPi in TNBC." (PMID 38459088, 2024). "Existing research has revealed that fibroblasts can promote the tumor drug resistance of ccRCCs through the TDO/Kyn/AhR signaling pathway, and they are positively correlated with tumor initiation and adverse prognosis." (PMID 38562930, 2024). "In tumor immune escape, AhR plays a key role in the immunosuppressive phenotype of the TME in cancer cells and is closely related to human amino acid metabolism as a sensor of tryptophan metabolites and is also a powerful immune system regulator." (PMID 38434684, 2024). "The AHR is a ligand binding transcription factor essential for effective NK cell migration into the tumour microenvironment, part of a network of receptors key to NK cell migration (e.g. chemokine receptors)." (PMID 38958472, 2024). "Herein, we review the impact of AhR on the tumor immune microenvironment, limitations of current findings, and the potential for modulation of AhR as a cancer therapy." (PMID 38339226, 2024). "For example, AhR activation can lead to the ubiquitination and degradation of AR, reducing its transcriptional activity and potentially inhibiting tumor growth." (PMID 39184676, 2024). "Studies have indicated that AhR acts as an environmentally sensitive transcription factor to facilitate tumor progression." (PMID 38410974, 2024). "The results suggest that IL4I1 is a tumor-produced metabolic enzyme that mainly catabolizes tryptophan to activate AHR, enhancing tumor aggressiveness and inhibiting anti-tumor immunity." (PMID 38755125, 2024). "Again, no discernible correlation was observed between the extent of immune cell infiltration in the tumor nest and AhR expression in the tumor region for either TAMs or T cells." (PMID 38680496, 2024). "As both CYP1A1 and COX-2 play a critical role in tumor initiation and promotion, the UV-activated AhR contributes to photo-carcinogenesis." (PMID 38518996, 2024). "The dichotomous impact of AhR on dendritic cells underscores the need for further studies to understand its true role in DC subsets and its impact on tumor immunity." (PMID 38339226, 2024). "Multiple lines of evidence suggest AhR exerts tumor suppressive effects in androgen-sensitive prostate cancer, with some mixed reports." (PMID 38807762, 2024).
tumor (continued). "Inhibiting AHR, particularly alongside PD-1 blockade, counters this effect and slows tumor progression, suggesting a tailored immunotherapeutic strategy that combines AHR inhibition with checkpoint inhibitors to overcome resistance in IDO/TDO-high cancers." (PMID 39461979, 2024). "By employing bioinformatic tools and machine learning techniques, a more detailed understanding of the AHR pathway’s involvement in immune regulation and tumor development has been achieved." (PMID 39835132, 2024). "Both tryptophan depletion and kynurenine-activated AHR transcription factors limit anti-tumour immunity by restricting T-cell activation, inducing Tregs and promoting myeloid cell tolerance." (PMID 38831013, 2024). "Several mechanisms by which AHR modulates the cell cycle have been proposed to account for the pro-/anti-proliferative action of AHR agonists observed with tumor cells in vitro." (PMID 38982523, 2024). "Nevertheless, the T-cell infiltration level in the tumor nest was positively correlated with AhR expression in cancer cells." (PMID 38680496, 2024). "In tumors overexpressing IDO/TDO, the tryptophan metabolite l-kynurenine activates the aryl hydrocarbon receptor (AHR) pathway, leading to increased immunosuppression via Tregs and tumor-associated macrophages, and enhanced PD-1 expression on CD8+ T cells." (PMID 39461979, 2024). "To determine how AHR activity in macrophages regulates the immunosuppressive PMN formation to facilitate 4T1 tumor colonization and regrowth, we detected immune cell subsets within the lung before metastasis formation." (PMID 39690159, 2024). "In the same study, it was found that, conversely, AhR pharmacological antagonism, as well as AhR deletion from myeloid cells, results in improved T-cell tumor infiltration, leading to tumor suppression." (PMID 38807762, 2024). "No clear pattern was found between the immune cell infiltration degree in the tumor nest and AhR expression in the tumor region for either TAMs or T cells." (PMID 38680496, 2024). "AhR mediates tobacco-induced PD-L1 expression on lung epithelial cells and tumor-repopulating cell-driven PD-1 upregulation in CD8+ T cells." (PMID 39042313, 2024). "In summary, MTH1 activity facilitates the alleviation of DNA damage in tumor cells via AhR-mediated ROS production." (PMID 38434684, 2024). "In several tumor types, the production of endogenous AhR ligands accelerates during disease progression, resulting in elevated intratumoral AhR activity in advanced disease." (PMID 38459088, 2024). "Although AhR was expressed in both the cytosol and nucleus of the tumor cells, its nuclear expression was generally higher." (PMID 38680496, 2024). "IFNγ expression can also lead to tumor-repopulating cells entering dormancy through upregulation of IDO1/aryl hydrocarbon receptor (AhR) dependent-p27 induction but prevents apoptosis." (PMID 38216787, 2024). "In the tumor microenvironment, KYN produced by IDO1 and TDO2 induces an immunosuppressive effect through AhR activation, influencing the tumor microenvironment and impairing the immune system's ability to recognize and eliminate tumor cells." (PMID 38883986, 2024). "Although AhR expression was also observed in Tregs, Treg infiltration varied depending on the tumor type, thereby influencing the results." (PMID 38680496, 2024). "The aryl hydrocarbon receptor (AhR) is a ligand-activated transcription factor that is widely recognized to play important, but complex, modulatory roles in a variety of tumor types." (PMID 38807762, 2024). "Activation of AhR with certain ligands has been shown to enhance AR-mediated transcription and promote tumor cell proliferation." (PMID 39184676, 2024).
tumor (continued). "An increasingly important role for AhR as a tumor promoter has been demonstrated in various head and neck cancers." (PMID 38807762, 2024). "The TME, a crucial location for cancer cell metabolism, is critical for AhR to regulate tumor metabolic reprogramming." (PMID 38434684, 2024). "Conversely, AhR can also inhibit AR signaling by recruiting corepressors or promoting AR degradation, thus suppressing tumor growth." (PMID 39184676, 2024). "Since AhR has been shown to be involved in carcinogenesis and tumor immunity, extensive studies have been conducted to elucidate the role of AhR in the tumor microenvironment (TME)." (PMID 38680496, 2024). "AhR can be upregulated by propranolol treatment in tumor tissue, which leads to the inhibition of Ki-67, a pro-metastatic biomarker." (PMID 38518996, 2024). "AhR, as a tumor suppressor, can be activated by controlling the expression of inflammatory cytokines, DNA damage, and cell proliferation." (PMID 38434684, 2024). "To investigate the impact of signals from the primary tumor on AHR activity in lung macrophages, we initially treated in vitro cultured macrophages with serum from control mice and mice bearing 4T1 tumors." (PMID 39690159, 2024). "Although numerous studies have demonstrated the detrimental effects of ligands like PAH and dioxins that activate the AhR, AhR activation can also result in tumor suppression and immunomodulation." (PMID 39339278, 2024). "Taken together, these studies show that activation of AhR enhances tumor cells’ ability to resist apoptosis." (PMID 38339226, 2024). "Several studies have explored the role of AhR expression in tumor progression and immune surveillance." (PMID 38680496, 2024). "Collectively, these results suggested that ILA contributes to the tumor-suppressive effect of B. breve lw01 via activating the macrophage AhR." (PMID 38773969, 2024). "More recently, it was also shown that Tph1 was induced in response to IL-2 in T cells in tumor microenvironment, leading to AhR nuclear translocation." (PMID 38509264, 2024). "Activation of the aryl hydrocarbon receptor in tumor-related macrophages by tryptophan-derived microbial metabolites suppresses anti-tumor immunity." (PMID 39170251, 2024). "The AHR plays diverse roles in cancer, exhibiting both tumour-promoting and tumour-suppressing activities." (PMID 39336758, 2024). "Further investigation is required to elucidate the mechanisms by which 4T1 cells dynamically influence AHR expression in macrophages, particularly at different stages of tumor progression." (PMID 39690159, 2024). "KYNA, tryptophan catabolite, can induce cancer cell invasion and inhibit tumor microenvironment by binding with AhR." (PMID 39408347, 2024). "K-means clustering and PCA were applied to individual tumor cores, each containing 13 features representing the AhR expression patterns, to identify meaningful clusters with significant components (P < 0.05; silhouette width = 0.45)." (PMID 38680496, 2024). "Our findings suggest that Jdp2 acts as a tumor suppressor gene upstream of the AhR–Nrf2 gene battery in a spatiotemporal manner." (PMID 38791215, 2024). "In AML, some reports suggest a tumor-promoting function of AhR, with high AhR expression and constitutive activity observed in AML patients." (PMID 38807762, 2024). "Given AhR's ability to modulate AR signaling bidirectionally and its independent effects on gene transcription and tumor cell proliferation, it holds potential as both a therapeutic target and a biomarker for disease aggressiveness." (PMID 39184676, 2024). "Filamin A ubiquitination is additionally key to Natural Killer (NK) cell migration to the tumour microenvironment, controlled by the aryl-hydrocarbon receptor (AHR)." (PMID 38958472, 2024).
tumor (continued). "AhR signals under different metabolic conditions have different effects on tumours, thus increasing the complexity of the ‘tryptophan metabolite‐AhR’ signalling pathway." (PMID 39568157, 2024). "One previous study revealed that tumor cells continuously produce kynurenic acid (Kyn), an endogenous ligand for the aryl hydrocarbon receptor (AHR), via tryptophan-2,3-dioxygenase (TDO)." (PMID 38244584, 2024). "Alternatively, binding of KYN to AHR increases PD‐1 expression on tumour‐specific CD8+ T cells and induces differentiation and activation of immunosuppressive Tregs and facilitates the recruitment of tolerogenic myeloid cells." (PMID 38935536, 2024). "AhR-expressing macrophages were not solely confined to the stroma, but were also identified within the tumor nest, representing a distinct AhR expression pattern in TAMs." (PMID 38680496, 2024). "Some authors have described that AhR activation can modulate the cell cycle by increasing cell proliferation and tumor growth in mice." (PMID 38745771, 2024). "Here, we summarize the current state of knowledge of the tumor modulatory roles of AhR based on varying cancer subsets." (PMID 38807762, 2024). "Given the well-recognized role of AhR as a regulator of tumor biology, many efforts are focused on developing therapeutic strategies to modulate AhR in cancer patients." (PMID 38807762, 2024). "Lactobacillus reuteri and indole-3-aldehyde (I3A) have been shown to modulate the tumor microenvironment via AHR, thereby enhancing anti-tumor immunity and optimizing immune checkpoint function in preclinical tumor models." (PMID 39575260, 2024). "The same study also examined the role of the aryl hydrocarbon receptor (AHR) which has been detailed to be a potential tumour suppressor and NLRP3 regulator." (PMID 39516433, 2024). "Not only does AhR have a function in the detoxification process, but numerous research demonstrate its role in immune response, cell cycle, metabolism, tumor proliferation, and reproduction." (PMID 38248350, 2024). "Previous research has discovered that AhR has a crucial role in lipid metabolism, nucleotide de novo synthesis, and tumor glycolysis." (PMID 38434684, 2024). "These genes are involved in many physiological functions, such as xenobiotic metabolism, immune response, cell cycle and proliferation, lipid metabolism, tumor promotion, and negative regulation of AHR pathway." (PMID 38982523, 2024). "Experiments with mouse models have confirmed that AhR inhibitors significantly inhibit tumor growth and synergize with PD-L1 antibodies." (PMID 38983930, 2024). "AhR signaling has been shown to impact immune checkpoint expression directly on tumor cells and within tumor-infiltrating lymphocytes." (PMID 38339226, 2024). "In the colon, AhR has dual roles in tumor suppression, by promoting the integrity of the epithelial barrier, dampening inflammation, and antagonizing proliferation signals downstream of Wnt/β-catenin during the regenerative process." (PMID 37106727, 2023). "Kynurenine present in tumor-conditioned media activate AHR (aryl hydrocarbon receptor) in macrophages, resulting in increased expression of CCR2 as well as recruitment of TAM." (PMID 37598273, 2023). "Unexpectedly, our findings imply that AHR itself possesses tumor suppressor-like property under the basal condition, and the carcinogenicity of As3+ is partially achieved through antagonizing the transcriptional activity of AHR." (PMID 37151890, 2023). "This review sought to summarize and discuss the various lines of evidence supporting AhR-dependent tumor-suppressive effects, with an emphasis on studies where endogenous AhR signaling opposed carcinogenesis in vivo." (PMID 37106727, 2023).